GSDMD (gasdermin D)
Diseases named in the same sentence as GSDMD in open-access papers (continued):
Sharing a sentence is not in itself a finding about the gene and the disease.
Sepsis (continued). "Further study found that the SV could inhibit GSDMD-mediated macrophage pyroptosis through the caspase-1-dependent signaling pathway, contributing to the resolution of the inflammatory response and lung injury in sepsis." (PMID 40028334, 2025). "Recent studies further suggest that extracellular vesicles carrying GSDMD pores integrate into neighboring cell membranes, propagating pyroptotic signals and initiating a cascade of inflammatory cell death, offering a novel mechanistic insight into systemic inflammatory dysregulation in sepsis." (PMID 40832104, 2025). "During sepsis, immunocyte pyroptosis may exert biological effects through classical pathways: Caspase-1 is activated, recognizes and cleaves GSDMD, after which the cleaved GSDMD forms pores in the cell membrane, ultimately triggering pyroptosis." (PMID 40364841, 2025). "Elevated levels of GSDMD-NETs axis biomarkers (N-GSDMD and MPO-DNA) were significantly associated with the incidence of SIC, mechanical ventilation requirement, and in-hospital mortality in sepsis patients, demonstrating a significant relationship with glycocalyx damage." (PMID 40766307, 2025). "Additionally, studies have investigated the role of GSDMD in sepsis-induced myocardial dysfunction, revealing that the accumulation of GSDMD-NT in cardiac tissue leads to mitochondrial dysfunction and excessive oxidative stress, which subsequently activates the NLRP3 inflammasome." (PMID 41550939, 2025). "The KEGG analysis results suggested that the differences between the two groups were mainly enriched in pertussis and TNF signaling pathway, demonstrating that hepatic GSDMD might play a role in the inflammatory response mediated by cytokines and secretory proteins in sepsis." (PMID 40856013, 2025). "Furthermore, GSDMD knockout mice exhibited improved behavioral outcomes after sepsis." (PMID 38627764, 2024). "Aberrant GSDMD activation triggers persistent inflammation and has been linked to the development of numerous inflammatory diseases, such as diabetes mellitus, liver diseases, cardiovascular diseases, neurodegenerative diseases, inflammatory bowel disease (IBD), and sepsis." (PMID 39253076, 2024). "Consequently, they and we propose that therapeutically targeting GSDMD to directly inhibit NETosis, or targeting upstream regulators of GSDMD to indirectly inhibit NETosis, may represent an efficacious strategy for the treatment of sepsis." (PMID 38584157, 2024). "Moreover, evidence suggests that GSDMD is involved in coagulation responses during sepsis." (PMID 38020710, 2023). "Hence, GSDMD is regarded as a promising target for sepsis treatment." (PMID 38020710, 2023). "Therefore, we speculated that the rs579501 CC-miR-27a-5p-GSDMD pathway is involved in sepsis progression." (PMID 36419831, 2022). "However, there are other signaling pathways that mediate NETs formation in sepsis except GSDMD-mediated pathway, such as oxidative stress and type I interferon signaling, It is not clear whether XBJ impact these pathways in neutrophils." (PMID 36467039, 2022). "Consequently, several studies demonstrated that GSDMD is of great importance in LPS-induced sepsis." (PMID 35774778, 2022). "Notably, during sepsis, the protein expression of GSDMA-NT, GSDMD-NT and GSDME-NT are reported to increase in sepsis-associated organ injuries, indicating that pyroptosis could play important roles in sepsis." (PMID 35967871, 2022). "Finally, blocking gasdermin D pore formation by Disulfiram treatment (an approved drug used to treat alcohol addiction, see last chapter) tapered LPS induced sepsis in mice: circulating levels of inflammatory cytokines were reduced and survival was greatly improved." (PMID 34831246, 2021).
Sepsis (continued). "And in this study, we observed severe pyroptosis and serious damage of the liver in septicemia-related liver injury in CD38-deficient mice, whereas both pyroptosis and damage of the liver can be significantly reversed in TLR4 mutant mice, accompanied by the decrease in NLRP3 and GSDMD." (PMID 33860064, 2021). "In this study, we found that pyroptosis related protein GSDMD in renal tubular epithelial cells was significantly increased during sepsis-induced AKI, suggesting that pyroptosis of renal tubular epithelial cells may be the key reason for the loss of renal tubular epithelial cell during AKI." (PMID 34222479, 2021). "In addition, NSA treatment significantly increased survival in LPS‐induced sepsis in vivo, suggesting that GSDMD inhibitors may show clinically efficacy in treating sepsis." (PMID 33033617, 2020). "Furthermore, a recently developed chemical inhibitor of gasdermin D, Necrosulfonamide improves survival following sepsis in mice arguing that gasdermin D inhibitors may be efficacious in treating certain inflammatory diseases." (PMID 31839993, 2019). "Genetic or pharmacological inhibition of GSDMD (e.g., by disulfiram, necrosulfonamide, dimethyl fumarate, or NU6300) reduces pyroptosis and improves survival in sepsis models, validating its therapeutic potential." (PMID 41536519, 2026). "During sepsis, RIPK3-mediated necroptosis synergizes with GSDMD-induced pyroptosis, amplifying inflammatory signaling and exacerbating tissue damage." (PMID 40832104, 2025). "In sepsis, DLL4+ neutrophils increase in the blood and lungs, upregulating ZBP1, cleaved gasdermin D, cleaved caspase-3, and phosphorylated MLKL, all of which are markers of PANoptosis, exacerbating ALI." (PMID 41392977, 2025). "By regulating the key molecule GSDMD, pyroptosis activates the NLRP3 inflammasome and caspase-1-dependent apoptosis, contributing to myocardial dysfunction in sepsis." (PMID 40526611, 2025). "Collectively, these results suggest that hepatocytic GSDMD is responsible for the release of HMGB1, ultimately resulting in systemic vascular injury and lethality in sepsis." (PMID 39927458, 2025). "Compared with the vehicle, the GSDMD activation inhibitor obviously reduced the mortality rate and plasma HMGB1 and IL-1β concentrations in the mice with sepsis." (PMID 39927458, 2025). "Besides interleukins, GSDMD pores mediate the release of extracellular cold‐inducible RNA binding protein (eCIRP) from living macrophages, suggesting that targeting GSDMD could be a novel and potential therapeutic approach to inhibit eCIRP‐mediated inflammation in sepsis." (PMID 40783818, 2025). "After the same IL‐6/LPS stimulation as above, the protein expression and ELISA results confirmed that the pore‐forming activity of GSDMD promoted the release of Gremlin‐1 and VEGF‐B from hepatocytes in sepsis." (PMID 40856013, 2025). "Inflammasome activation in sepsis, particularly through the NLRP3 complex, directly induces pyroptosis through GSDMD cleavage by caspase-11 in murine models, or caspase-4/5 in humans in response to cytosolic LPS." (PMID 40959087, 2025). "Our results demonstrated that pyroptosis occurred in the liver in the sepsis model induced by both LPS and CLP, evidenced by a significant increase in the expression levels of cleaved‐GSDMD, cleaved‐caspase‐1, and cleaved‐caspase‐11." (PMID 40856013, 2025). "This drug inhibits septic neutrophil gasdermin D (GSDMD) activation and reduces NET release, thereby improving sepsis-induced organ damage and survival in septic mice." (PMID 40861493, 2025). "In sepsis, the release of HMGB1 into the bloodstream by immune cells mediates the activation of caspase‐11 and GSDMD, leading to a hypercoagulable state, the induction of DIC, and resulting in multiple organ failure." (PMID 39445002, 2024). "Nonetheless, the function of GSDMD in pyroptosis, NET release, and the onset of sepsis is complex, necessitating additional studies to comprehensively delineate its mechanisms of action." (PMID 38584157, 2024).
Sepsis (continued). "Gasdermin-D (GSDMD) acts as an executioner of pyroptosis and is activated by Caspase-11 (a human homologous of Caspases-4/5) during sepsis." (PMID 37962578, 2024). "In an induced sepsis animal model, a study was conducted to inhibit the expression of GSDMD and its lysed form GsdMd-NT by administering the caspase-1 inhibitor VX765 as a neuroprotective therapy to reduce pyrodeath of brain cells during sepsis." (PMID 39027435, 2024). "MVs from bronchoalveolar lavage fluids (BALFs) of sepsis or acute lung injury (ALI) models induced NETs formation, which was partly inhibited by the GSDMD inhibitor, disulfiram." (PMID 38169726, 2024). "The results demonstrated that PBMCs from the sepsis group had significantly higher relative protein levels of NLRP3, caspase-1, cleaved GSDMD, and IL-1β than those from the control groups." (PMID 38169584, 2024). "Other articles showed that the miR-31-5p/GSDMD Axis can regulate pyroptosis and miR-31-5p overexpressing can alleviate the level of TNF‐α, IL‐6 and IL‐1β in sepsis-induced pyroptosis." (PMID 38267979, 2024). "During gram‐negative bacteria infection, caspase‐11 activated by cytosolic LPS cleaves GSDMD, and the released N‐GSDMD mediates both pyroptosis and NLRP3 inflammasome activation, which promotes sepsis." (PMID 37090118, 2023). "Several GSDMD inhibitors, including disulfiram, necrosulfonamide (NSA), and dimethyl fumarate (DMF), have been shown to be effective in relieving sepsis." (PMID 37275856, 2023). "Inhibited oligomerization of GSDMD and cell pyroptosis by scavenging RONS in endotoxin-induced sepsis." (PMID 38022612, 2023). "We demonstrated that genetic deletion of GSDMD in neutrophils efficiently reduced NET release and attenuated the progression of SAE in CLP-induced sepsis model." (PMID 37056920, 2023). "Similar positive feedback loops have been identified in sepsis, where RIPK3 and GSDMD signaling co-diffuse to amplify the inflammatory response and cytokine release in macrophages and endothelial cells." (PMID 38002346, 2023). "Then, we find that genetic deletion of neutrophil GSDMD or PD-L1 reduces NET release and improves SAE in murine sepsis model." (PMID 37056920, 2023). "ALA reduced the level of NETs, pyroptosis-related proteins (Cl-caspase-1, Cl-GSDMD, ASC), and IL-1β in the lung tissue of sepsis mice." (PMID 37051243, 2023). "It has been also reported that GSDMD can be cleaved in neutrophils from septic mice and humans, playing a crucial role in NET release and organ dysfunction during sepsis 27-29." (PMID 37056920, 2023). "The expression of NLRP3, Caspase-1, GSDMD, IL-1β, and IL-18 was decreased, suggesting that ALDH2 also inhibited pyroptosis in sepsis-induced lung injury." (PMID 35188436, 2022). "In 2021, there were new developments in disulfiram, an FDA-approved targeted drug for NETs and pyroptosis, which inhibited septic neutrophil GSDMD activation and reduced NET release, thereby improving sepsis-induced organ damage and survival in septic mice." (PMID 36059483, 2022). "We previously revealed that GSDMD-mediated pyroptosis and RIPK3-mediated necroptosis in both myeloid and nonmyeloid cells critically contributed to the progression of sepsis." (PMID 35941120, 2022). "Targeting Gasdermin D (GSDMD) can restrain NETs formation, which is promising for sepsis management." (PMID 36467039, 2022). "Therefore, we wondered whether XBJ impacts the expression of GSDMD in sepsis-induced lung injury." (PMID 36467039, 2022). "However, the role of GSDMD in sepsis-induced cardiac dysfunction remains unknown." (PMID 34820388, 2021). "The results showed that the levels of caspase-11, GSDMD-NT, NLRP3, ASC, caspase-1, IL-1β, and IL-18 were increased in sepsis mice and that ST pre-treatment suppressed this effect." (PMID 34483936, 2021). "In view of the potential synergistic impact on sepsis-induced injuries, one study aimed to investigate the protective effect on double deletion of RIPK3 and GSDMD." (PMID 34824200, 2021).
Sepsis (continued). "During sepsis, GPX4 was proposed to inhibit phospholipase C gamma 1-mediated GSDMD activity and caspase-dependent events, therefore reducing excessive macrophage pyroptosis." (PMID 34824200, 2021). "While little information about this exists, our data show that sepsis-triggered canonical inflammasome depends on the NLRP3/caspase-1 pathway for the maturation and secretion of IL-1β and on GSDMD for the induction of pyroptosis." (PMID 30276509, 2019). "In this context, disruption of TLR sensing or conformational activation of NLRP3, GSDMD, STING, or other related pathways may influence sepsis progression." (PMID 40461967, 2025). "Therefore, endothelial GSDMD mediates the regulatory effects of the HMGB1/RAGE axis on vascular injury and death in sepsis." (PMID 39927458, 2025). "Contrary to previous studies that GSDMD plays a negative role in sepsis, we found that liver‐specific knockout of GSDMD aggravated inflammatory responses and lung injury in both LPS‐ and CLP‐induced sepsis model." (PMID 40856013, 2025). "During sepsis, GSDMD activation in neutrophils, but not monocytes, is relevant to multiple organ dysfunction." (PMID 38436813, 2024). "This is the first study to assess the ability of pyroptotic macrophage-derived MVs to mediate NETs formation by transferring GSDMD-N-expressing mitochondria and triggering the mtROS/GSDMD axis, which contributes to organ dysfunction and systemic coagulation during sepsis." (PMID 38169726, 2024). "In relation to the phenomenon of platelet pyroptosis, investigations conducted on mice lacking platelet-specific GSDMD revealed that GSDMD serves as a trigger for platelet pyroptosis in sepsis induced by CLP." (PMID 38654328, 2024). "Firstly, we found that CD14+ monocytes from pneumonia-induced sepsis patients had considerably greater levels of the proteins TLR4, NLRP3, ASC1, cleaved caspase-1, IL-1, and GSDMD in contrast to pneumonia patients without sepsis and healthy people." (PMID 36923408, 2023). "As an inhibitor of GSDMD, disulfiram could inhibit NET release during sepsis 27, and had been involved in a clinical trial to treat SARS-CoV-2 infection." (PMID 37056920, 2023). "The activation of noncanonical inflammasomes induces GSDMD cleavage and pyroptosis, which play an important role in the pathogenesis of bacterial infections and sepsis." (PMID 37275856, 2023). "Furthermore, rhodopsin has been shown to decline the expression of NLRP3 and GSDMD in myocardial tissues, suppressing the activation of the NLRP3 inflammasome and ultimately reducing septic myocardial injury in an LPS-induced sepsis model." (PMID 38161332, 2023). "Since anaplastic lymphoma kinase (ALK) activates STING during sepsis, it is expected that clinically used ALK inhibitors (e.g., ceritinib) might block GSDMD activation in macrophages." (PMID 36209190, 2022). "Thus, besides NOMID, FMF, EAE, and sepsis, PTOA is another experimental disease model in which ablation of GSDMD attenuates tissue damage." (PMID 34784954, 2021). "However, another study pointed out that upregulated GSDMB in patients with sepsis and Crohn’s disease promoted caspase-4 activity and GSDMD cleavage, revealing a GSDMB-regulated novel regulatory mechanism for GSDMD-induced pyroptosis in inflammatory diseases." (PMID 34858408, 2021). "Blood assays revealed that when primed with the TLR3 agonist poly(I:C), LPS-induced coagulation factor III (F3) release and lethal coagulation in mice suffering from sepsis required CASP11 but not CASP1-mediated GSDMD activation." (PMID 34858408, 2021). "Several mechanisms of the release of exosomal HMGB1 from cells have been revealed so far, such as the activation of TLR4 and caspase-11/gasdermin D (GSDMD) signaling, decreased autophagy and endoplasmic reticulum (ER) stress, all of which are important cellular mechanisms of sepsis pathophysiology." (PMID 33013905, 2020).
Sepsis (continued). "Consistent with this concept, mice with caspase-1/-11 or gasdermin D gene deletion, thus lacking inflammasome activation and pyroptosis, are resistant to endotoxin-induced sepsis." (PMID 27812336, 2016). "Furthermore, GSDMD targeting the ER is responsible for calcium leakage, which in turn facilitates the translocation of HMGB1 from the nucleus to the cytosol, rendering this DAMP available for release in sepsis." (PMID 40783818, 2025). "Based on the cell membrane pore‐forming effect of GSDMD, we speculated that hepatic GSDMD might release Gremlin‐1 and VEGF‐B from hepatocytes into the serum through cell membrane pores, thereby alleviating sepsis." (PMID 40856013, 2025). "Combining NLRP3/GSDMD inhibitors with NET/MET modulators may reduce inflammation, microthrombosis, and multiorgan failure in sepsis and COVID-19, provided it is applied within the optimal therapeutic window, guided by biomarkers and adaptive precision clinical trials." (PMID 40959087, 2025). "Additionally, LL-37 has been shown to alleviate sepsis-induced acute lung injury by downregulating the expression of key components of the pyroptotic pathway, including NLRP3, caspase-1, and GSDMD, as well as downstream inflammatory factors in alveolar epithelial cells." (PMID 40072070, 2025). "Inhibiting endothelial GSDMD-mediated pyroptosis, rather than decreasing the myeloid cell GSDMD pyroptosis-triggered cytokine storm, prevents vascular injury and death in endotoxemia and sepsis." (PMID 39927458, 2025). "However, sepsis-induced nuclear autophagy was inhibited in GSDMD−/− mice, and the upregulation of LC3B was observed in both cytoplasmic and nuclear components, implying that GSDMD was involved in the process of nuclear autophagy." (PMID 36979288, 2023). "Our study revealed that in sepsis, the degradation of nuclear LaminB could be suppressed in the absence of GSDMD." (PMID 36979288, 2023). "In conclusion, this study found that ceramide-mediated endothelial pyroptosis depends on the activation of ROS-dependent TXNIP/NLRP3/GSDMD signalling, and TXNIP inhibition may provide an important adjuvant therapeutic approach for alleviating vascular endothelial injury in sepsis and other diseases." (PMID 36517743, 2022). "In addition, activation of GSDMD mediates phosphatidylserine exposure, boosts the coagulation cascade, and promotes the process of disseminated intravascular coagulation (DIC), a complication mediating organ dysfunction or even death in sepsis." (PMID 34093202, 2021). "Moreover, mRNA expression of STING1 and GSDMD in peripheral blood mononuclear cell (PBMC) closely correlates with DIC severity in patients with sepsis, highlighting the regulatory role of STING1 in DIC during sepsis." (PMID 33796108, 2021). "In LPS‐ and CLP‐induced sepsis models, we found that hepatic GSDMD did not exacerbate liver injury in septic mice, as well as the dysfunction of the liver, so we speculated that in addition to playing a pyroptotic role, hepatic GSDMD played other roles in sepsis, such as pore‐forming activity." (PMID 40856013, 2025). "In addition, qPCR results showed that the mRNA levels of GSDMD, IL‐1β, caspase‐1, and caspase‐11 in liver tissues were significantly increased in LPS‐ and CLP‐induced sepsis models, and the serum concentration of IL‐1β in the sepsis model was also significantly increased." (PMID 40856013, 2025). "However, during sepsis progression, if the UPR cannot reestablish cellular equilibrium, the endoplasmic reticulum stress (ERS) response shifts to a proapoptotic mode; the key nuclear caspase-1, which recognizes and processes gasdermin-D (GSDMD), is upregulated, leading to pyroptosis." (PMID 40153575, 2025). "GSDMD also has been confirmed as a key regulator and a therapeutic target in several diseases, like multiple sclerosis (MS), experimental autoimmune encephalomyelitis (EAE), cryopyrin-associated periodic syndromes (CAPS), and Gram-negative bacteria–induced sepsis." (PMID 35774778, 2022).